RAC1P4 (Rac family small GTPase 1 pseudogene 4)
Synonyms: Psi4Rac1; formerly RAC4
Gene: Processed pseudogene on chromosome X (137,441,258 to 137,441,836, reverse strand). Ensembl gene ENSG00000237584.
Diseases named in the same sentence as RAC1P4 in open-access papers:
RAC1P4 is named in the same sentence as 2 diseases in open-access papers, as found by Europe PMC text mining. Sharing a sentence is not in itself a finding about the gene and the disease.
RAC1P4 shares sentences with these, for which no sentence is quoted: bacterial infection (1 paper); Intellectual disability (1).